MYC (MYC proto-oncogene, bHLH transcription factor)
Diseases named in the same sentence as MYC in open-access papers (continued):
Sharing a sentence is not in itself a finding about the gene and the disease.
hepatocellular carcinoma (511 papers, 2004 to 2026). A malignant tumor that arises from hepatocytes. "Recently, it has been reported that USP13-mediated deubiquitination is associated with MYC in cholangiocarcinoma, glioma stem cells, and hepatocellular carcinoma." (PMID 38093367, 2023). "The amplification of c-MYC was observed during the development of hepatocellular carcinoma, which was associated with impaired survival." (PMID 34335109, 2021). "MYC's effect on glutaminolysis was cohesive in the various cancer types, with an associated increase demonstrated in hepatocellular carcinoma, pancreatic ductal adenocarcinoma, and renal cell carcinoma." (PMID 32292719, 2020). "Moreover, transcriptional analysis of endothelial cells from MYC knockout mice showed functions associated with liver hyperplasia/hyperproliferation and hepatocellular carcinoma." (PMID 38510176, 2024). "In esophageal tumor cells miR-26a/b were shown to be involved in a feedback loop with c-MYC that causes a decrease of proliferation, whereas in hepatocellular carcinoma they acted as tumor suppressor sensitizing chemoresistant cancer cells to drug-induced apoptosis." (PMID 33362864, 2020). "The effect MYC has on glycolysis is highly variable depending on the cancer type, with a MYC-associated increase in non-small cell lung cancer and hepatocellular carcinoma, and a MYC associated decrease in renal cell carcinoma and prostatic intraepithelial neoplasia." (PMID 32292719, 2020). "In addition, we found that ATIII treatment reduced induction of the transcription factor MYC, expression of which has been associated with progression of liver disease to chronic hepatitis, cirrhosis, and hepatocellular carcinoma." (PMID 23031791, 2012). "PHAROH (Pluripotency and Hepatocyte Associated RNA Overexpressed in HCC), can modulate MYC translation by interacting with and sequestering the translation repressor nucleolysin TIAR in hepatocellular carcinoma." (PMID 39075086, 2024). "The MYC oncogene itself is frequently up-regulated in liver disease, where it drives metabolic reprogramming and contributes to fibrosis and hepatocellular carcinoma." (PMID 41497980, 2025). "Previous research has demonstrated that IGF-II knockdown can suppress MYC expression in hepatocellular carcinoma cells via the FAK/PI3K/AKT signaling pathway." (PMID 40160318, 2025). "For instance, HDAC3 ubiquitination by the E3 ligase TRAF6 leads to MYC upregulation in hepatocellular carcinoma due to dissociation of K63-ubiquitinated HDAC3 from the MYC promoter." (PMID 40305047, 2025). "This is in accord with previous studies showing upregulation of MYC in hepatocellular carcinoma through dissociating K63-ubiquitinated HDAC3 from the MYC promoter." (PMID 40305047, 2025). "BPTF is a target and regulator of MYC and exerts pro-tumourigenic functions in diverse cancers including melanoma, hepatocellular carcinoma, or ovarian cancer." (PMID 40633141, 2025). "In hepatocellular carcinoma, silencing BRD4 or MED1 repressed the transcription of SE-associated genes like SPHK1, E2F2, CCND1, MYCN, and MYC." (PMID 38443991, 2024). "(G) Alternative splicing: Zhou demonstrated that an intron 3 retention transcript of lncRNA PXN-AS1 (PXN-AS1-IR3) recruits p300 to the MYC promoter, activating MYC downstream genes and facilitating hepatocellular carcinoma (HCC) metastasis." (PMID 39443468, 2024). "The ratio of CD44+ CD62L+ central memory (TCM) cells was higher in hepatocellular carcinoma (HCC) tumors from MYC‐ON mice as well as in colon tumors from CT‐26 allograft mice after DU101 or DU102 treatment in comparison with DMSO treatment." (PMID 39225354, 2024). "In hepatocellular carcinoma, the promotion of increased nutrient transport via MYC indirectly contributes to the activation of polyamine biosynthesis by mTORC1." (PMID 37443779, 2023).
hepatocellular carcinoma (continued). "Lai and co-authors created IL-12-LNP nanoparticles loaded with mRNA of interleukin-12 (IL-12) for the in situ delivery of this cargo in a primary transgenic mouse model of refractory MYC-driven hepatocellular carcinoma." (PMID 37109432, 2023). "MYC and Twist1 cooperate to drive metastasis by initiating crosstalk between hepatocellular carcinoma and innate immunity." (PMID 36639679, 2023). "Among them, INPP5F has been recently demonstrated to be an oncogene that activates the ASPH-mediated Notch-c-MYC/cyclin E1 pathway in hepatocellular carcinoma." (PMID 37469520, 2023). "mTORC1 activates MYC to promote hepatocellular carcinoma tumorigenesis by modulating methionine metabolism." (PMID 37173935, 2023). "For example, TRIP13 plays an oncogenic role in glioblastoma via the FBXW7/c-MYC pathway and induces hepatocellular carcinoma (HCC) cell migration, invasion, and metastasis through AKT/mTOR signaling via and interaction with ACTN4." (PMID 38012658, 2023). "In CRC and hepatocellular carcinoma (HCC), the truncation of the 3′ UTR of MYC caused a loss of the repressor miR-138-binding site, which contributed to oncogene activation." (PMID 37443779, 2023). "A recent study reported that PRMT5 negatively regulated MHC-II expression in MYC-driven hepatocellular carcinoma." (PMID 35493527, 2022). "PXN-AS1-IR3 recruits Tex10 and p300 to the MYC enhancer region to promote MYC transcriptional activation, thereby promoting the migration and invasion of hepatocellular carcinoma." (PMID 35992805, 2022). "MYC is a notorious oncogene in a vast network of malignancies, whereas liver-specific microRNA- (miR-) 122-5p is downregulated in hepatocellular cancer (HCC)." (PMID 36033372, 2022). "Paradoxically, we found in a MYC–driven hepatocellular carcinoma model that systemic buffering increased tumor mTORC1 activity, negating inhibition of tumor growth by anti-PD1 treatment." (PMID 36380966, 2022). "In hepatocellular carcinomas, oncogene MYC induces FAM83H transcription, and the increased expression of FAM83H stimulates the growth and invasiveness of cells." (PMID 35885485, 2022). "Repression of MYC results in the reversal of tumorigenesis in various in vivo mouse models, including T-cell acute lymphoblastic leukemia, hepatocellular carcinoma, osteosarcoma, among others." (PMID 34448104, 2022). "In HBV/HCV-associated hepatocellular carcinoma, HCV upregulates the expression of ß-catenin and MYC, and HBV upregulates the expression of EPCAM, ß-catenin and MYC and activates nuclear factor κ-B (NF-κB) signaling." (PMID 35359592, 2022). "PRMT5 silencing in MYC-overexpressing hepatocellular carcinoma cells directly regulated MHC-II expression by decreasing the in vitro H3R8me2s and H4R3me2s enrichment on CIITA and CD74 promoters." (PMID 35493527, 2022). "In the study reported here, we found that systemic buffering by oral NaHCO3 paradoxically negated the effect of anti-PD1, an immune checkpoint inhibitor, in an inducible MYC–driven mouse hepatocellular carcinoma (HCC) model." (PMID 36380966, 2022). "Though intriguing, tumor cells derived from MYC-induced breast and hepatocellular carcinoma were reverted into a dormant state." (PMID 33958005, 2021). "In summary, our data suggest that PHAROH regulates MYC translation by sequestering TIAR and as such represents a potentially exciting diagnostic or therapeutic target in hepatocellular carcinoma." (PMID 34002693, 2021). "Similar to the results of this study, RBP-AGO2 promoted the proliferation of hepatocellular carcinoma cells by binding and stabilizing the transcription factor MYC mRNA." (PMID 34819492, 2021). "FAM83H is transcriptionally controlled by the well-known oncogene MYC and regulates the proliferation of hepatocellular carcinoma cells." (PMID 34625065, 2021).
hepatocellular carcinoma (continued). "In a phase Ib/II clinical trial (NCT02314052) the safety and tolerability ability to inhibit MYC of DCR-MYC were evaluated in patients with advanced hepatocellular carcinoma." (PMID 34863235, 2021). "For example, in hepatocellular carcinoma CD73 expression regulates hepatocellular cancer stem cells via the AKT-c-MYC axis." (PMID 33430239, 2021). "Its enhanced expression level disrupts the reverse regulation of MYC gene expression in hepatocellular carcinoma cells, creating conditions for consistently high MYC expression." (PMID 34440124, 2021). "For example, in gastric cancer cells, the ceRNA HOXC-AS1 binds miR-590-3p, in colon cancer cells the ceRNA SNHG3 suppresses miR-182-5p activity, and ceRNA Linc00176 blocks the binding of miR-9 and miR-185-5p to MYC mRNA in hepatocellular carcinoma cells." (PMID 34440124, 2021). "Similar observations have been reported in SW620 cells, U-1906 cells, MYC-induced murine liver tumors, lung adenocarcinoma, murine renal cell carcinoma, human hepatocellular carcinoma, as well as in MYC-activated U266-derived cells." (PMID 34503295, 2021). "Gene silencing using a shRNA library identified the requirement of CDK9 for the sustained proliferation of hepatocellular cancer cells and their dependence on MYC." (PMID 34041038, 2021). "Recently, an isoform switch from KHKC to KHKA mediated by a c-MYC-mediated upregulation of the splicing factors HNRNPH1/2 has been shown to promote the progression of hepatocellular carcinoma in human cells." (PMID 32733884, 2020). "Regarding the use of mRNA to deliver IL-12 locally, a recent study demonstrated that weekly i.v. delivery of lipid nanoparticles (LNP) loaded with mRNA encoding IL-12 reduced tumor burden in a MYC-driven transgenic mouse model of hepatocellular carcinoma (HCC)." (PMID 33178203, 2020). "CDK9 inhibitors demonstrate efficacy in downregulating MYC transcripts and Myc stability across hepatocellular carcinoma, mixed-lineage leukemia, diffuse large B-cell lymphoma, acute myeloid leukemia, and pancreatic cancer." (PMID 33322239, 2020). "We generated an autochthonous transgenic mouse model whereby conditional expression of MYC and Twist1 enables hepatocellular carcinoma (HCC) to metastasize in >90% of mice." (PMID 31933479, 2020). "CDK9 is a potential target as it is part of P-TEFb, is necessary for proliferation and maintenance of MYC-overexpressing hepatocellular carcinoma, and is required for maintenance of gene silencing in several cancer cell lines." (PMID 33322239, 2020). "Disease progression in hepatocellular carcinoma was found to be associated with global transcriptomic imbalance due to oncogenic activation of NELFE and enhanced MYC signaling." (PMID 33154494, 2020). "Previously, we reported that PGG inhibits MYC expression both at mRNA as well the protein level in human hepatocellular carcinoma cells (Kant, 2017, unpublished data)." (PMID 29472861, 2018). "Recently, our group showed that PGG inhibits MYC expression in hepatocellular carcinoma (Kant, 2017, unpublished data)." (PMID 29472861, 2018). "In fact, c-MYC knockdown in PDAC cells increased IFN-γ-induced PD-L1 expression, in agreement with a recent study showing that c-MYC knockdown in hepatocellular carcinoma cells results in increased IFN-γ-induced PD-L1 expression." (PMID 30185888, 2018). "For example, in hematopoietic tumors, osteosarcomas and hepatocellular carcinomas, inactivation of the oncogene MYC induced cellular senescence as an important mechanism of sustained tumor regression." (PMID 29796172, 2018). "The antitumor effect of JQ1 through MYC repression was also shown in neuroblastoma, medulloblastoma, hepatocellular carcinoma, and acute myeloid leukemia." (PMID 28881656, 2017).
hepatocellular carcinoma (continued). "In human neurons, GLS1 expression was upregulated by IL-1β or TNF-α treatment, and in a rat hepatoma model IL-6 or TNF-α treatment indirectly upregulated c-MYC expression." (PMID 28399896, 2017). "Removal of doxycycline leads to MYC induction in the liver and development of tumors that resemble human hepatocellular cancer." (PMID 28273073, 2017). "A SCCA-1-mediated (both direct and indirect) MYC overexpression has recently been demonstrated in hepatocellular carcinoma." (PMID 28042960, 2017). "Recently, the roles of FAM83H in tumorigenesis have been interested and increased expression of FAM83H and MYC in hepatocellular carcinoma (HCC) have been reported." (PMID 28607447, 2017). "The present study provided a model to explain the the differential transcriptional regulation of tumor suppressor let-7 by oncogene MYC in glioblastoma and hepatocellular carcinoma." (PMID 27409345, 2016). "CDK9 as a therapeutic target for MYC driven cancer was demonstrated in a shRNA library screening in which CDK9 was required for the aberrant proliferation of MYC overexpressing hepatocellular carcinoma cell lines." (PMID 27486754, 2016). "It has been reported that the expression c-MYC gene is elevated in liver carcinoma HepG2 cells compared to the normal human liver cells." (PMID 26286633, 2015). "This is in well agreement with the reduced activity of c-MYC in liver carcinoma cells after treatment with BTC f." (PMID 26286633, 2015). "Small molecule carcinogens, shRNA, and partial hepatectomy have all been demonstrated in separate studies to contribute to MYC-induced hepatocellular carcinoma using the same model and similar methods to those used in this study." (PMID 20614008, 2010). "Furthermore, in hepatocellular carcinoma models, higher nuclear C7 expression upregulates stemness-associated genes (OCT4, SOX2, and MYC) through LSF-1 activation." (PMID 40806542, 2025). "c-MYC endows hepatocellular carcinoma (HCC) cells with a malignant phenotype." (PMID 38699229, 2024). "Previous work has shown that there is a specific increase in expression of CTLA4, a negative regulator of T-cell receptor signaling, during tumor progression in a KRAS-driven murine PDAC model and that induction of MYC in a model of hepatocellular carcinoma elevates CTLA4 expression on T-cells." (PMID 38365788, 2024). "Epigenetically induced myc interacting lncRNA 1 (EPIC1) promotes the development of the hepatocellular carcinoma cell cycle by interacting with myc proto-oncogene, bHLH transcription factor (MYC), and overexpression of EPIC1 correlates with a poor prognosis in hepatocellular carcinoma patients." (PMID 38139458, 2023). "Here, we employ the use of the quadratic phenotypic optimization platform (QPOP) to characterize and narrow down effective combinations of targets which mediate the best possible treatment outcomes in MYC‐driven hepatocellular carcinoma (HCC) as our disease model of choice." (PMID 36684069, 2023). "Abnormal WNT/β-catenin pathway can be observed in a variety of cancers like breast cancer, colorectal cancer, and hepatocellular carcinoma, which often acts as the upstream carcinogenic signal of MYC and participates in the process of proliferation, apoptosis, and angiogenesis." (PMID 36966168, 2023). "In addition, in MYC-induced hepatocellular carcinoma, FASN suppressed by gene silencing or soluble inhibitors inhibited proliferation and induced apoptosis." (PMID 37151387, 2023). "In addition, studies have confirmed that SLC38A4 is a prospective biomarker with therapeutic goal that exerts tumor suppressive effects in hepatocellular carcinoma by modulating the Wnt/β-catenin/MYC/HMGCS2 axis." (PMID 37168445, 2023). "Deregulation of MYC is among the most frequent oncogenic drivers in hepatocellular carcinoma (HCC)." (PMID 36684069, 2023). "In addition, TRIM21 is involved in regulating ACTL6A/MYC axis activity in hepatocellular carcinoma progression." (PMID 37171396, 2023).
hepatocellular carcinoma (continued). "In fact, in human hepatocellular carcinoma cells, MYC represses the expression of the let-7a cluster by binding to the non-canonical E-box and, in the brain, MYC represses the expression of the miR-23 cluster, which may result in a reduction in myelination." (PMID 36359259, 2022). "Moreover, the authors found that enforcing MYC expression in human hepatocellular carcinoma‐derived cells increased the sensitivity to PHA‐767491, a CDK9‐inhibitory tool compound." (PMID 36214609, 2022). "Our research preliminarily proves that FBL could affect the proliferation, stemness, migration, and invasion of hepatocellular carcinoma cells, which might be involved in the activation of MYC and E2F signaling." (PMID 36004921, 2022). "In addition, glycyrrhizin, a commonly used HMGB1 inhibitor, significantly inhibited the expression of HMGB1 and thus c-MYC, thereby suppressing hepatocellular carcinoma." (PMID 36193082, 2022). "A comparative analysis of miR-122 interactors in different pathways describes the presence of several genes associated with CRC including SMAD4, TGFBR1, AKT, MYC, Rho, Ras, Raf, Bax, and CDK 4/6 to actively engage in hepatocellular carcinoma and other pathways of cancer." (PMID 36499586, 2022). "Therefore, we aimed to illuminate the function of the lin28B/Let-7c/MYC axis in hepatocellular carcinoma." (PMID 36057607, 2022). "Similarly, data from mouse tumor models with hepatocellular carcinoma and melanoma have revealed that MYC amplification was correlated with low CYT and few T-cell infiltration." (PMID 35898926, 2022). "Similarly, in MYC-induced murine hepatocellular carcinoma, GLS1+/− heterozygotes had smaller tumor loads than their wild-type GLS1+/+ counterparts." (PMID 34503295, 2021). "Furthermore, the silencing of CDK9 inhibited MYC-dependent liver tumorigenesis in a mouse model and suppressed the proliferation of xenografts of murine and human hepatocellular cancer cells." (PMID 34041038, 2021). "Notably, HMGCR is a positive regulator of phosphorylation, activation, and tumorigenic properties of MYC in a MYC-driven model of hepatocellular carcinoma where exogenous mevalonate deliver can enhance cancer growth." (PMID 33718197, 2021). "Moreover, FAM83H is thought to be involved in hepatocellular carcinoma progression by controlling the transcription of MYC." (PMID 34625065, 2021). "Indeed, while MYC-induced murine liver carcinoma displays a significant increase of glucose and glutamine catabolism, MYC-induced lung adenocarcinoma shifts towards glutamine accumulation." (PMID 32932943, 2020). "In another study, interaction between IRE1α and RACK1 was crucial for the activation of IRE1α/XBP1 signalling upon unfolded protein response induced by sorafenib in hepatocellular carcinoma cells, further supporting the interconnection between MYC signalling and ER processes." (PMID 32878211, 2020). "In hepatocellular carcinoma, MYC inactivation leads tumor cells to differentiate and many of them to die, but some cells showed stem cell properties and regained their proliferative capacity upon MYC reactivation." (PMID 32046751, 2020). "In addition, FAM83H is expected to have an oncogenic role because its transcription is regulated by the oncogene MYC and it mediates MYC-related proliferation of hepatocellular carcinoma cells." (PMID 30723706, 2019). "In addition, the suppression of lipogenesis and cholesterol metabolism by HSF1 suppression in an AKT and c-MYC-driven hepatocellular carcinoma model has been observed." (PMID 31540279, 2019). "As for hepatocellular carcinoma, there is a hypothesis that c-MYC mainly regulates controlling PGK1 expression." (PMID 28749413, 2017). "Moreover, it also indicated the importance of NF-κB, RAS and JNK activation in early hepatoma formation.The role of MYC in various types of carcinogenesis has been extensively investigated." (PMID 20540791, 2010).